RAG2 (recombination activating 2)
Diseases named in the same sentence as RAG2 in open-access papers (continued):
Sharing a sentence is not in itself a finding about the gene and the disease.
clostridium difficile infection (1 paper, 2019). Symptomatic infection due to the spore-forming bacterium clostridium difficile. "Previous study demonstrated innate lymphoid cells were a critical role against Clostridium difficile infection based on data from Rag1-/- single gene and Rag2/IL2rg-/- double gene mutated mice." (PMID 31134127, 2019).
co-infection (1 paper, 2020). "Collectively, these results indicate that co-infection with Hp in RAG2 males preferably enhanced gene expression of ILC1s and ILC3s-associated colonic cytokines." (PMID 33255175, 2020). "In spite of the absence of Hp-induced gastric pathology in RAG2 mice, our data demonstrated that co-infection with Hp in Hh-infected RAG2 male mice significantly promoted Hh-induced preneoplastic lesions in the colon but not in the cecum by 21 WPI." (PMID 33255175, 2020). "In contrast, this co-infection in RAG2 females downregulated expression of several cytokines such as Il-1β, Il-17A, Ifnγ, Tnfα, and Il-13 only at 10 WPI, but increased transcription of colonic Il-22 at 21 WPI." (PMID 33255175, 2020). "In this study, we tested whether co-infection with gastric Hp affected Hh-induced intestinal carcinogenesis in RAG2 mice." (PMID 33255175, 2020). "In conclusion, we demonstrated that co-infection with Hp promoted Hh-induced colonic carcinogenesis in male RAG2 mice despite the lack of overt Hp gastric pathology." (PMID 33255175, 2020). "Interestingly, co-infection with Hp promoted Hh-induced intestinal pathology in the colon of RAG2 males but not in the cecum where Hh colonization levels (~107) were higher compared to the colon (~106)." (PMID 33255175, 2020).
complement deficiencies (1 paper, 2021). "Recently, a significant number of genes have been implicated in monogenic lupus, such as several complement deficiencies, ACP5, DNASE1, DNASE1L3, PRKCD, RAG2 genes, etc.." (PMID 34796153, 2021).
cryptosporidiosis (1 paper, 2023). Intestinal infection with organisms of the genus Cryptosporidium. "To better define functions of innate IELs in cryptosporidiosis, we developed a co-culture model with innate IELs isolated from Rag2-/- mice and 3D intestinal organoids infected with C. parvum using microinjection." (PMID 37744354, 2023). "Indeed, a recent work showed that ILC1s limit the expansion of the parasite in Rag2-/- animals through their secretion of IFN-γ.Yet, the role of innate IELs in cryptosporidiosis remains poorly studied." (PMID 37744354, 2023).
cystitis (1 paper, 2015). Inflammation of the urinary bladder. "We employed a model of UPEC-induced cystitis in which 107 colony-forming units (CFU) of UPEC isolate UTI89, made resistant to either ampicillin or kanamycin, were instilled intravesically into 7–8 week old female wildtype C57Bl/6 or C57Bl/6 RAG2-/- mice." (PMID 26182347, 2015).
dengue fever (1 paper, 2024). "RAG2-/-γc-/- human CD34+, NSG-A2 and NSG-BLT models are potentially valuable for investigating the mechanisms underlying dengue-induced ADE." (PMID 39312399, 2024). "Additionally, RAG2-/-γc-/- (RAG2 -hu) and RAG2-/-γc-/- human CD34+ have been tested for dengue fever immune pathogenesis and antibody neutralizing activity." (PMID 39312399, 2024).
diarrheal disease (1 paper, 2016). The condition of having at least three loose or liquid bowel movements each day. "Of interest, although the level of shedding and the severity of diarrheal disease have been directly correlated in children, this correlation is not invariable since the Rag2-/- mice resolved diarrhea while continuing to shed RV." (PMID 27128797, 2016).
E. coli infection (1 paper, 2022). "Furthermore, adoptive transfer of B cells into Rag2-/- mice aggravated liver damage upon E. coli infection in sensitive and reestablished tissue protection in tolerant mice." (PMID 36178806, 2022).
food allergy (1 paper, 2025). Gastrointestinal disturbances, skin eruptions, or shock due to allergic reactions to allergens in food. "Rag23−3 mice are a cross between OVA23−3 mice and Rag2 knockout mice and are used as a model of food allergy, whereas RagD10 mice are a cross between DO11.10 mice and Rag2 knockout mice and are used as a model of oral tolerance." (PMID 40446078, 2025).
Gliosis (1 paper, 2018). Gliosis is the focal proliferation of glial cells in the central nervous system. "Similarly, the Rag2 KO mice might be vulnerable to other diseases, such as organismal injury and abnormalities including cancer and gliosis, along with renal dysfunction." (PMID 29495457, 2018).
glomerulonephritis (1 paper, 2019). A renal disorder characterized by damage in the glomeruli. "Crossing the ABIN1[D485N] mice to RAG2 KO mice not only abolished glomerulonephritis but also lung inflammation, indicating that the pathology of both of these organs requires the adaptive immune system." (PMID 31694920, 2019). "We found that glomerulonephritis measured at 6 mo of age was completely suppressed in ABIN1[D485N] × RAG2 KO mice." (PMID 31694920, 2019). "Glomerulonephritis in ABIN1[D485N] × RAG2 KO mice was undetectable up to 6 mo of age, indicating that a functional adaptive immune system is required for this phenotype to develop." (PMID 31694920, 2019). "Surprisingly, and in contrast to our findings in ABIN1[D485N] × RAG2 KO mice, the ABIN1 KO × RAG1 KO mice, which also lack T and B cells, still developed glomerulonephritis." (PMID 31694920, 2019).
granulocytosis (1 paper, 2012).
Hyperglycemia (1 paper, 2012). An increased concentration of glucose in the blood. "The RAG2 KO, RIP-HA Tg recipients developed hyperglycemia by 8–10 days after cell transfer, whereas those receiving either CD4+ (Foxp3-GFP) +/− T-reg cells from the same F1 donors or CD4 splenic T-reg cells from Foxp3-GFP+/+ Tg parental mice did not." (PMID 22723880, 2012).
Hyperinsulinemia (1 paper, 2021). An increased concentration of insulin in the blood. "We thus evaluated glucoregulatory capacity in RAG2−/− mice fed either diet for 6 weeks and observed a partial protection against WD-induced 5 h fasted hyperinsulinemia, insulin secretion during OGTT, body weight gain, and total fat mass." (PMID 33597537, 2021).
hypothyroidism (1 paper, 2025). Abnormally low levels of thyroid hormone. "Importantly, euthyroid Rag2-/- mice showed accelerated clinical manifestations and a higher disease score than their euthyroid WT counterparts; and hypothyroidism further exacerbated disease symptoms." (PMID 41263555, 2025).
Infertility (1 paper, 2016). "Pregnant Rag2-/- γc -/- mice do not reproduce the whole spectrum of preeclampsia, fetal growth restriction, infertility or miscarriage." (PMID 27736914, 2016).
ischemia (1 paper, 2019). A hypoperfusion of the BLOOD through an organ or tissue caused by a PATHOLOGIC CONSTRICTION or obstruction of its BLOOD VESSELS, or an absence of BLOOD CIRCULATION. "We next studied the expression of proteins involved in BBB function and vascular integrity in Rag2−/− mice subjected to ischemia and treated with either fingolimod or vehicle, and non-ischemic Rag2−/− mice that were used as controls." (PMID 31165772, 2019).
liver disease (1 paper, 2016). "Further, the failure to develop the inflammatory and fibrotic liver disease of the single transgenic 24αNOD.Rag2-/- and 24βNOD.Rag2-/- mice provided evidence that the formation of a complete TCR and thus the generation of a functional NKT cell population was required for the disease to develop." (PMID 27441847, 2016).
lymphoid tumours (1 paper, 2016). "As the CD4NA/RAG2−/−/OTI transgenic mice do not develop lymphoid tumours, it was possible that RAG was acting as an essential tumour promoter in the NPM–ALK/OTI mouse." (PMID 26753883, 2016).
microcephaly (1 paper, 2009). A congenital or acquired developmental disorder in which the circumference of the head is smaller than normal for the person's age and sex. "RAG1, RAG2, and DCLRE1C are the primary genes responsible for the T-B-NK+ SCID phenotype and in a recent report, mutations in LIG4 were also documented in patients with this phenotype who also have microcephaly and developmental delay." (PMID 19912631, 2009).
motor neuron disease (1 paper, 2017). "On the other hand, SOD1 transgenic mice with additional depletion of the Rag2 gene (mSOD1/RAG2−/− mice) show delayed motor neuron disease, thus suggesting that mature lymphocytes produce deleterious effects on vulnerable motor neurons." (PMID 29081763, 2017).
muscular dystrophy (1 paper, 2017). Muscular dystrophy (MD) refers to a group of more than 30 genetic diseases characterized by progressive weakness and degeneration of the skeletal muscles that control movement. "The therapeutic potential of DPPSC was tested in a wound healing mouse model and in two genetic mouse models of muscular dystrophy (Scid/mdx and Sgcb-null Rag2-null γc-null)." (PMID 28750661, 2017).
neuroblastoma (1 paper, 2025). Neuroblastoma (NB) is the most common solid, extracranial childhood tumor. "However, the excellent efficacy of indisulam to C-MYC tumors in Rag2-/- mice suggests that the innate immunity, including NK cells can be leveraged to develop more effective therapies against neuroblastoma." (PMID 40962798, 2025). "Similarly, indisulam treatment led to complete and durable responses in human neuroblastoma xenografts (SK-N-AS) implanted into Rag2-/- mice." (PMID 40962798, 2025). "Considering the genetic background difference between NSG mice and Rag2-/- or C57BL/6 mice, we therefore directly assess whether NK cells can be activated by indisulam to enhance neuroblastoma cell killing." (PMID 40962798, 2025).
pancreatic adenocarcinoma (1 paper, 2021). "We have developed RAG2/IL2RG deficient pigs using CRISPR/Cas9 as a large animal model with the novel application of cancer xenograft studies of human pancreatic adenocarcinoma." (PMID 33828203, 2021).
preeclampsia (1 paper, 2016). Preeclampsia is a hypertensive disorder of pregnancy that is characterized by new-onset hypertension with proteinuria presenting after 20 weeks of gestation, and depending on mild or severe forms may initially present with severe headache, visual disturbances, and hyperreflexia. "Although Rag2-/-γc-/- mice do not present with hypertension or growth restriction as noted in severe preeclampsia, they constitute a representative model to examine the early stages of preeclampsia development." (PMID 27736914, 2016).
Rett syndrome (1 paper, 2025). A severe neurodevelopmental disorder affecting the central nervous system.
Rotavirus infection (1 paper, 2016). Infection with any of the rotaviruses. "We used mouse strains deficient in type-specific IFN signaling, STAT1 and Rag2 to dissect distinct and overlapping contributions of type I and type III IFNs to protection against homologous murine (EW-RV strain) and heterologous (non-murine) simian (RRV strain) rotavirus infections in suckling mice." (PMID 27128797, 2016).
Salmonella Infections (1 paper, 2024). Infections with bacteria of the genus SALMONELLA. "To evaluate if IEL were the main cells mediating the protective effects of Gzms against Salmonella infection, we adoptively transferred WT or GzmA/B dKO IEL to Rag2-/- (RAG2 KO) mice." (PMID 39137883, 2024).
Sjögren’s syndrome (1 paper, 2022). "Furthermore, it has been reported that patients with systemic lupus erythematodes (SLE), Sjögren’s syndrome, RAG1 and RAG2 deficiency and X-linked immunodysregulation polyendocrinopathy enteropathy (IPEX) can generate type I IFN auto-antibodies." (PMID 35986347, 2022).
smallpox (1 paper, 2015). A condition that is caused by infection with Variola, and that is characterized by small, raised bumps. "Therefore, the rTV-Fluc/SD rats and rTV-Fluc/Rag2-/- rats are suitable visualization models, which recapitulate wild type or immunodeficient populations respectively, for testing human smallpox vaccine and antiviral drugs." (PMID 26235050, 2015). "Therefore, rTV-Fluc/Rag2-/- rats can serve as a faithful model of immunodeficient population infected with human smallpox to evaluate the safety and efficacy of OPV antiviral drugs." (PMID 26235050, 2015).
soft tissue sarcoma (1 paper, 2022). A malignant neoplasm arising from muscle tissue, adipose tissue, blood vessels, fibrous tissue, or other supportive tissues excluding the bones. "High mutational load transplant soft tissue sarcomas were initiated in Rag2+/− and Rag2−/− mice to model varying lymphocyte burden." (PMID 35314638, 2022).
steatosis (1 paper, 2022). Increased lipid within the cytoplasm of cells. "A recent study has shown that Il2rg-/-/Rag2-/-/Fah-/- mice with a humanized liver fed a high fat diet (41% kcal fat) developed higher steatosis than mice fed a control diet." (PMID 35533183, 2022).
Thrombocytopenia (1 paper, 2019). A reduction in the number of circulating thrombocytes. "We showed that depletion of macrophages reduced cytokine generation and alleviated thrombocytopenia in Rag2 KO rats." (PMID 31921873, 2019).
thymic tumors (1 paper, 2010). "Our data indicated that thymic tumors occurred more frequently in the Rag2-deficient background and the immune system of a normal immunocompetent mouse may be able to eliminate the P1A-induced tumor." (PMID 20976169, 2010).
type 2 diabetes (1 paper, 2020). "Given that DR3 stimulation can protect from the onset of type 2 diabetes, we next examined the therapeutic potential of DR3 agonistic treatment in a model of Rag2−/− mice with previously established type 2 diabetes." (PMID 32948777, 2020).
typhoid fever (1 paper, 2013). A bacterial infectious disorder contracted by consumption of food or drink contaminated with Salmonella typhi. "Using a chimeric rag-2 deficient mouse with humanized hematopoietic stem and progenitor cells may help to shed light on the so far insufficiently understood immune response and development of immunity to typhoid fever and finally lead to more reliable tests and better vaccines." (PMID 24099396, 2013).
Wolfram syndrome (1 paper, 2023). Wolfram syndrome (WS) also known as DIDMOAD, is a neurodegenerative disorder characterized by type I diabetes mellitus (DM), diabetes insipidus (DI), sensorineural deafness (D), bilateral optical atrophy (OA) and neurological signs. "To extend our findings to an in vivo humanised Wolfram syndrome model, we transplanted iPSC-derived beta cell aggregates from two WFS1-deficient individuals and an isogenic control under the kidney capsule of immunodeficient Rag2 KO mice." (PMID 36995380, 2023).
ZIKV infection (1 paper, 2023). "Since only a subset of immunocompetent mice are susceptible to ZIKV infection and able to survive postnatally, and interferon deficient mice lack a critical component of the innate immune system, we developed a Rag2-/-γc-/- neonatal humanized mouse model for CZS." (PMID 36825016, 2023).
tumor (171 papers, 2003 to 2026). "Methodically, the implantation of human tumor cells into immune-compromised mice (e.g., nude or severe combined immune-deficiency mice, such as NOD scid γ mice (NSG) or NOD Rag2 γc mice (NRG)) allows studying tumor growth in a physiological 3D environment." (PMID 39948421, 2025). "We implanted KP-HetLow tumor cells in wildtype, Rag2-/- and Batf3-/- mice, and observed a loss of tumor control in Rag2-/- and Batf3-/- mice, indicating that cDC1 are required for the induction of effective T cell responses." (PMID 37548358, 2023). "To determine the influence of the level of HLA‐E surface expression on the malignant cells, we inoculated HLA‐Elow (non‐transfected) and HLA‐Ehigh (transfected) Cal‐27 tumor‐cell variants on opposite flanks of Rag2−/‐IL2Rγ−/− mice." (PMID 37782273, 2023). "Next, we show results from a recently developed immunocompromised RAG2/IL2RG deficient pig tumor model that better mimics human anatomy and physiology compared to mouse models." (PMID 34478363, 2022). "Future and on-going studies will utilize these data to refine and optimize orthotopic tumor engraftment with these cell lines in the RAG2/IL2RG deficient pigs." (PMID 34478363, 2022). "Adaptive immunity was unable to constrain the growth of KP tumours asthey grew at similar rates in immune-competent(Rag2+/-) and immune-deficient(Rag2-/-) mice." (PMID 35930804, 2022). "Tumor iodine concentration was the only significantly different conventional tumor metric between Rag2+/− (TLs present) and Rag2−/− (TL-deficient) tumors." (PMID 35314638, 2022). "Tumor growth in lymphocyte deficient RAG2−/− animals was accelerated when compared to wild-type animals both upon mock and IL-35+ DC vaccination, confirming the involvement of lymphocytes in the CMT93 cancer model." (PMID 28228759, 2017). "We further evaluated the contribution of the acquired immune system to tumor suppression of P29mtSAMP1 cybrids using B6 Rag2-/- (T and B cell–deficient) mice, which have a defective acquired immune system due to deficiency of the recombination-activating gene." (PMID 24098752, 2013). "HPV8-CERtg mice crossed with Rag2-deficient mice, to recreate the immunosuppressive tumor microenvironment similar to that observed in organ transplant recipients on immunosuppressants, demonstrated accentuated tumor growth." (PMID 38916963, 2024). "Subcutaneous tumor growth has been demonstrated in a proof-of-principle study with implantation of human PC cells (Panc01) into the ears of immunodeficient transgenic pigs (RAG2/IL2RG deficient)." (PMID 36579622, 2023). "Interestingly, immunogenicity of AML keeps changing during tumor evolution, showing a trend that the aggressive AMLs generate through serial transplantations are susceptible to NK cell-mediated tumor suppression in Rag2−/− mice." (PMID 38129572, 2023). "We subcutaneously transplanted either B16F10 tumor or LLC tumor into RAG2-deficient recipient mice." (PMID 33564072, 2021). "To determine what types of cells in the Wnt1 tumors express SDF1, we injected dissociated Wnt1 tumor cells into the mammary fat pads of immune-deficient Rag2−/−mice constitutively expressing an enhanced green fluorescent protein under control of the chicken β-actin promoter (EGFPtg/Rag2−/−)." (PMID 20087418, 2010). "We found that Ehmt2 knockdown resulted in significantly reduced tumor growth inhibition in Rag2 KO mice." (PMID 41366520, 2026). "To further determine the importance of NK cells in Ehmt2 knockdown-mediated tumor growth inhibition in vivo, we injected Ehmt2 knockdown Panc02 cells into Rag2 knockout (Rag2 KO) mice, which lack T and B cells but have NK cells." (PMID 41366520, 2026). "To examine how COX2 inhibition affects the immune TME, we treated RTT tumour-bearing Rag2–/– mice with celecoxib, adoptively transferred T cells intravenously and performed scRNA-seq." (PMID 39604727, 2025).